NPTX2 (neuronal pentraxin 2)
Diseases named in the same sentence as NPTX2 in open-access papers (continued):
Sharing a sentence is not in itself a finding about the gene and the disease.
Cognitive impairment (continued). "Furthermore, NPTX2 in CSF was the only biomarker that was associated significantly with MMSE score in AD patients, outperforming previously established biomarkers (e.g., p‐Tau181), which serves as evidence of its robustness as a cognitive impairment marker." (PMID 40522075, 2025). "Therefore, the objective of this study is to investigate the relationship between serum NPTX2 concentrations and cognitive performance in elderly diabetic patients, with the aim of identifying early indicators of cognitive impairment and potential targets for intervention." (PMID 40694319, 2025). "Therefore, when the pathophysiological role of NPTX2 levels in cognitive impairment in patients with diabetes is fully proven, the current biomarkers may guide both rapid and early diagnosis and the development of an effective treatment modality via NTPX2." (PMID 40694319, 2025). "Similarly, NPTXR and NPTX2, neuronal pentraxins that regulate glutamatergic synaptic transmission and synapse formation, were significantly decreased, indicating progressive synaptic dysfunction and excitatory neurotransmission deficits characteristic of AD-related cognitive impairment." (PMID 41292640, 2025). "NPTX2 levels are lower in the CSF of FTD patients, and reduced CSF NPTX2 levels can be used as a predictor of cognitive impairment in AD." (PMID 39258226, 2024). "Neuronal pentraxin 2 (NPTX2), a recently identified synaptic biomarker linked to cognitive disorders, has not previously been examined in relation to cognitive function in geriatric individuals with diabetes." (PMID 40694319, 2025). "Lower levels of the secreted glycoproteins NPTX1 and NPTX2 are related to more severe non-motor PD symptoms and cognitive deficits, measured by MDS-UPDRS part I, supporting previous findings in PD33,36,37." (PMID 38760408, 2024). "Proteins that could distinguish cognitive impairment were mainly neuronal proteins (VGF, NPTX2, NPTXR, and SCG2)." (PMID 37160957, 2023).
pancreatic cancer (22 papers, 2008 to 2025). "Hypermethylation of NPTX2 in pancreatic cancer tissue may constitute a molecular diagnostic marker, and NPTX2 methylation levels in tumoral tissue have been associated with poor survival in PDAC patients." (PMID 37481552, 2023). "Previous studies have shown a diagnostic value of NPTX2 hypermethylation in pancreatic cancer." (PMID 29212200, 2017). "In particular, in pancreatic cancer, Neuronal pentraxin II (NPTX2) has been observed to be hypermethylated; thus, methylation of NPTX2 might provide a novel diagnostic marker for pancreatic cancers." (PMID 24084722, 2013). "The frequent hypermethylation and significantly lower mRNA and protein expression levels of NPTX2 were previously reported in pancreatic cancer and glioblastoma than in paired normal tissues." (PMID 38254821, 2024). "Previous studies also showed that the importance of DNA methylation (such as cyclin D2, ppENK, NPTX2) in pancreatic juice for the diagnosis of pancreatic neoplasms." (PMID 24714692, 2014). "Quantitative RT-PCR revealed that the mean mRNA expression level of NPTX2 in the pancreatic cancer tissues was significantly lower than that in the paired adjacent normal tissues (0.96 ± 0.91 vs. 2.78 ± 1.42, p < 0.001)." (PMID 24084722, 2013). "Analysis revealed that the promoter region of the NPTX2 gene was largely unmethylated in normal pancreatic tissues, while NPTX2 was frequently hypermethylated in pancreatic cancer cells and in primary pancreatic carcinomas." (PMID 24084722, 2013). "Of the validated genes, Neuronal Pentraxin II (NPTX2) methylation has been shown to be upregulated in pancreatic cancer, and its expression is increased in Parkinson's disease." (PMID 21731603, 2011). "These genes include UCHL1 (methylated in 100% of 42 pancreatic cancers), NPTX2 (98%), SARP2 (95%), CLDN5 (93%), reprimo (86%), LHX1 (76%), WNT7A (71%), FOXE1 (69%), TJP2 (64%), CDH3 (19%), and ST14 (10%)." (PMID 19424480, 2008). "Although no publications explicitly link NPTX2 methylation to lung cancer development, it has been reported that NPTX2 functions as a tumor suppressor in various solid cancers, such as pancreatic cancer, prostate cancer, glioblastoma, and thymic epithelial tumors." (PMID 39123492, 2024). "However, NPTX2 was down-regulated and correlated with the poor prognosis of pancreatic cancer and glioma due to its promoter hypermethylation." (PMID 33768003, 2021). "AlthoughNPTX2 showed a lower expression due to its promoter hypermethylation and identified poor prognosis in glioma and pancreaticobiliary cancer, only one study demonstrated the direct effect of NPTX2 on the inhibiting proliferation and invasion of pancreatic cancer cells." (PMID 33768003, 2021). "NPTX2 is a member of the neuronal pentraxin family 36 and is strongly expressed in tissues of numerous cancer types, including malignant gliomas, lung cancer, and pancreatic cancer." (PMID 34258887, 2021). "With regard to pancreatic cancer, DNA methylation markers, cyclin-dependent kinase inhibitor 2A (CDKN2A/p16), ras-associated domain family member 1 (RASSF1A) and neuronal pentraxin 2 (NPTX2) in cfDNA are considered diagnostic markers." (PMID 32520974, 2020). "In pancreatic cancer, NPTX2 expression is silenced by DNA hypermethylation." (PMID 26831905, 2016). "Nptx2 is one of genes reported with aberrant DNA methylation in familial pancreatic cancers." (PMID 21362171, 2011). "Therefore, NPTX2 may act as a tumor suppressor in not only pancreatic cancer and glioblastoma, but also TC." (PMID 38254821, 2024). "Meanwhile, the methylation status of NPTX2, BMP3 and SPARC genes plays an important role in the prognosis of pancreatic cancer." (PMID 39497722, 2024). "First, we have analyzed in cfDNA from eight mPDAC patients the methylation levels of five genes BMP3, NPTX2, SPARC, TFPI2 and SFRP1 known to be aberrantly methylated in pancreatic cancer." (PMID 37481552, 2023).
pancreatic cancer (continued). "For example, the genes SPARC, UCHL1, NPTX2, PENK, and PDAC were investigated in pancreatic cancer, where they were found to be hypermethylated in patients with pancreatic cancer." (PMID 34771655, 2021). "Increasing evidence demonstrates that NPTX2 acts as either an oncogene or tumor suppressor in different tumor types, being significantly upregulated in colorectal cancer (CRC) 14 and frequently downregulated in pancreatic cancer 15 compared to control tissue." (PMID 35069913, 2022). "After conducting a thorough analysis of published studies on cfDNA methylation in pancreatic cancer, as well as a comparative methylation analysis using the TCGA database, we have identified a set of consistently reported hypermethylated genes: BMP3, NPTX2, SFRP1, SPARC, and TFPI2." (PMID 37481552, 2023). "Furthermore, methylation promoter areas in the cfDNA of pancreatic cancer patients have been found for the genes SPARC (secreted protein acidic and rich in cysteine), UCHL1 (ubiquitin carboxy terminal hydrolase L1), PENK (proenkephalin), and NPTX2 (neuronal pentraxin 2)." (PMID 39200847, 2024).
dementia (12 papers, 2017 to 2025). Loss of intellectual abilities interfering with an individual's social and occupational functions. "Serum NPTX2 levels have been analyzed in previous studies and have been found to be altered in individuals with acute psychotic episodes in schizophrenia and to be associated with cognitive function in patients with dementia." (PMID 40868076, 2025). "It is further notable that both NPTX2 down-regulation and fMRI functional connectivity similarly correlate with clinical Dementia Rating scores." (PMID 28440221, 2017). "Furthermore, in genetic frontotemporal dementia, low CSF NPTX2 levels predicted subsequent decline in phonemic verbal fluency and Clinical Dementia Rating scale." (PMID 32807227, 2020). "Additionally, CSF levels of NPTX2 are reduced in patients with AD dementia and MCI, compared to controls and correlate with cognitive performance." (PMID 31231205, 2019). "Importantly, NPTX2 levels in AD subjects correlated with cognitive performance employing comprehensive psychometric tests including the Dementia Rating Scale, and surpassed the performance of other CSF markers including Aß42, tau and p-tau." (PMID 28440221, 2017). "There was a significant interaction with group for SYT1, NPTX1, NPTX2, and NPTX-R; slopes of AD dementia patients (st.B[SE] –0.15[0.05], –0.11[0.04], –0.13 [0.04], and –0.10[0.04] respectively) differed from those of SCD/MCI-A– subjects." (PMID 39121126, 2024). "Meanwhile, both dementia groups featured starkly decreased levels of known neuroprotective markers VGF and NPTX2, which are consistently decreased in the brains of those with neurodegeneration." (PMID 39107789, 2024). "Higher NPTX2 was associated with higher CSF levels of both total tau (t-tau, a marker of general neurodegeneration) and phosphorylated tau (p-tau, a marker of neurofibrillary tau tangles) within both cognitively normal and AD-dementia patients, but not with CSF abeta 1-42 levels." (PMID 31231205, 2019). "Previous studies have shown an association of lower levels of in NPTX2 and VGF with worse cognition in non-demented individuals with AD and conversion to dementia." (PMID 40033427, 2025). "In line with our results, decreases in NPTX2 and VGF have previously been associated with worse cognition in non-demented individuals with AD and conversion to dementia." (PMID 39108495, 2024).
Parkinson disease (11 papers, 2011 to 2025). A progressive degenerative disorder of the central nervous system characterized by loss of dopamine producing neurons in the substantia nigra and the presence of Lewy bodies in the substantia nigra and locus coeruleus. "Agreeing with the role of alpha-synuclein at presynapses, several genes annotated for the Gene Ontology-slim term synapse showed differential expression, some of them previously associated with Parkinson's disease including Nptx2, Wnt7a, and Rims3." (PMID 29755323, 2018). "One study found that NPTX2 plays an urgent role in Parkinson's disease, and another study found that the level of CSF synaptic protein named NPTX2 considerably declines in AD patients." (PMID 36793451, 2023). "Here we should note that other diseases, such as Parkinson’s Disease and late-stage liver cancer exhibit increased NPTX2 levels; thus, NPTX2 modulators are needed." (PMID 36743910, 2022). "This further enriches the mechanisms by which NPTX2 participates in the pathogenesis of Parkinson's disease." (PMID 32748547, 2020). "Not only in epilepsy, Lang and his colleagues found that NPTX2 plays an important role in Parkinson's disease." (PMID 32748547, 2020). "In a mouse model of Parkinson’s disease, HOTAIR drives autophagy in midbrain dopaminergic neurons by enhancing NPTX2 (neuronal pentraxin 2) expression through binding to Mir221-3p." (PMID 39684286, 2024). "To date, CSF NPTX2 levels have not been reported in other neurodegenerative diseases, such as sporadic FTD and Parkinson’s disease." (PMID 32273328, 2020). "To date, CSF NPTX2 levels in other neurodegenerative diseases have not been reported; future research should focus on the measurement of CSF NPTXs across a broader range of neurodegenerative diseases, including sporadic FTD and Parkinson’s disease." (PMID 32273328, 2020).
frontotemporal dementia (9 papers, 2019 to 2024). Frontotemporal dementia (FTD) comprises a group of neurodegenerative disorders, characterized by progressive changes in behavior, executive dysfunction and language impairment, as a result of degeneration of the medial prefrontal and frontoinsular cortices. "In particular, neuronal pentraxin 2 is described as the earliest biomarker to become detectably abnormal, as compared to other CSF markers, in presymptomatic carriers of gene mutations related to frontotemporal dementia." (PMID 36321699, 2023). "Examine NPTX2 in other neurodegenerative disorders, for example, Frontotemporal Lobar Degeneration and Dementia with Lewy Bodies." (PMID 31853477, 2019). "Notably, NPTX2 was consistently misaccumulated in neurons from patients with amyotrophic lateral sclerosis and frontotemporal lobar degeneration with TDP-43 pathology." (PMID 38355792, 2024). "A newly published study points out that NPTX2 is significantly lower in genetic frontotemporal dementia (FTD) and is a novel synaptic marker to predict the progression of FTD disease." (PMID 32748547, 2020). "When NPTX2 is overexpressed in neurons in the Tau P301S model of frontotemporal dementia (FTD) and Alzheimer’s Disease (AD), the level of the complement C4b and synapse engulfment decreases, leading to increased number of excitatory synapses on parvalbumin interneurons." (PMID 39258226, 2024). "Several biomarker discovery studies using mass spectrometry methods have identified changes in CSF levels of NPTX2 or NPTX1 in AD and decreased Neuronal Pentraxin Receptor in Frontotemporal Dementia." (PMID 31853477, 2019). "NPTX2, also known as neuronal activity-regulated protein, has been reported to have reduced CSF levels in various neurodegenerative diseases such as AD, genetic frontotemporal dementia (FTD), and dementia with Lewy bodies (DLB), correlating with cerebral atrophy and cognitive dysfunction." (PMID 38566855, 2024).
colorectal cancer (8 papers, 2019 to 2024). A primary or metastatic malignant neoplasm that affects the colon or rectum. "NPTX2 was shown to be overexpressed in colorectal cancer tissues in this investigation, and T stages were connected to increased NPTX2 expression, lymph node invasion, distant metastases, clinical step, and bad prognosis in colorectal cancer patients." (PMID 35310907, 2022). "NPTX2 promoted the proliferation and metastasis of colorectal cancer cells through interacting with FZD6." (PMID 33618667, 2021). "As for colorectal cancer, renal cell carcinoma and neuroblastoma, all studies demonstrate the direct carcinogenesis effects of NPTX2." (PMID 33768003, 2021). "Meanwhile, NPTX2 is a synaptic protein involved in malignancy via dysregulation of the cell cycle, apoptosis, and the Wnt/β-catenin pathway, in ovarian carcinoma, colorectal cancer, and UL." (PMID 36703136, 2023). "NPTX2 mRNA and protein expression levels were previously reported to be significantly higher in colorectal carcinoma (CRC), clear cell renal cell carcinoma (ccRCC), and neuroblastoma than in normal tissue." (PMID 38254821, 2024). "Herein, we found that NPTX2 mRNA and protein expression was significantly upregulated in colorectal carcinoma (CRC)." (PMID 30833544, 2019). "In the present study, we found NPTX2 expression was upregulated in CRC, which promotes colorectal cancer growth and liver metastasis by the activation of the canonical Wnt/β-catenin pathway via FZD6." (PMID 30833544, 2019). "NPTX2 could serve as an oncogene in RCC, neuroblastoma and colorectal cancer." (PMID 34565284, 2021).
glioblastoma (8 papers, 2017 to 2025). The most malignant astrocytic tumor (WHO grade IV). "In contrast to our finding, hypermethylation of NPTX2 has been correlated with poor survival in glioblastoma." (PMID 29212200, 2017). "In glioblastoma NPTX2 has been shown to inhibit AKT which in turn represses NFKB activity." (PMID 38875182, 2024). "Moreover, NPTX2 was proposed as an unrecognized prognostic biomarker and target in human neuroblastoma, and a risky methylated gene in glioblastoma, even though its methylation was not investigated in RCC yet." (PMID 34565284, 2021).
neuroblastoma (7 papers, 2019 to 2024). Neuroblastoma (NB) is the most common solid, extracranial childhood tumor. "A study evaluating the relationship between NPTX2 expression and cancer prognosis found that NPTX2 was overexpressed in human neuroblastoma stage IV and was positively associated with poor prognosis." (PMID 30833544, 2019). "Other studies revealed correlations between high NPTX2 mRNA and protein expression levels and the proliferation and metastasis of ccRCC and neuroblastoma." (PMID 38254821, 2024). "Targeting NPTX2 with the selected peptide can reduce the tumor burden in orthotopic mouse models of human neuroblastoma." (PMID 33768003, 2021). "NPTXR and NPTX2 are overexpressed in human Schwannian stroma-poor neuroblastoma, and NPTX2 expression serves as a marker of poor prognosis of neuroblastoma patients." (PMID 32847597, 2020). "The NPTX2/NPTXR system was shown to be upregulated in neuroblastoma and promote tumor development." (PMID 30833544, 2019). "Interestingly, studies have also shown that high levels of NPTX2 expression may be a biomarker for poor prognosis in human neuroblastoma." (PMID 32748547, 2020). "Collectively, these findings suggest that NPTX2 has as oncogenic function in CRC, ccRCC, and neuroblastoma, as well as in NECTT." (PMID 38254821, 2024). "They found that blockade of ligand-receptor connection between NPTX2 and NPTXR reduces tumor burden in orthotopic mouse models of human neuroblastoma." (PMID 32847597, 2020).